CRP (C-reactive protein)
Diseases named in the same sentence as CRP in open-access papers (continued):
Sharing a sentence is not in itself a finding about the gene and the disease.
COVID-19 (continued). "In order to investigate the relationship of the Ct value of viral RNA with neutrophil, lymphocyte count, and CRP in COVID-19 patients, we performed a linear regression analysis." (PMID 34122620, 2021). "We also found a notable decrease of albumin and increase of CRP in COVID-19 patients, especially in ICU patients, which is consistent with a recent study." (PMID 33640878, 2021). "Recent data have shown that insulin requirements are increased and correlated with high CRP serum levels and COVID-19 severity." (PMID 34124187, 2021). "We compared protease inhibitor concentration based on current and future COVID-19 severity and with C-reactive protein." (PMID 34458849, 2021). "Changes in CRP concentration seen in COVID-19 are likely reflective of robust inflammatory responses and cytokine release, however, our results indicate their utility to also predict the presence of significant microbiology and potential bacterial coinfection." (PMID 34496795, 2021). "We explored the relationship between serum neuronal injury biomarkers and age, time from COVID-19 infection to sampling, disease severity (CRP) and hypoxia across all individuals with COVID-19." (PMID 34396099, 2021). "Elevated VWF antigen and activity levels have been documented in COVID-19.9, 11, 20Likewise, inflammatory markers such as CRP and IL-6 are known to be elevated in COVID-19." (PMID 33709050, 2021). "NET release can be triggered by various inflammatory mediators found elevated in severe COVID-19, including CRP, IL-1β, IL-6 and IL-8." (PMID 33684134, 2021). "There was a previous history of cognitive impairment, older age, and higher levels of creatine-kinase and C-reactive protein after admission for COVID-19 for many patients with seizures." (PMID 34078305, 2021). "Another study also demonstrated that the in-hospital mortality rate was 29.2% (33/113 patients) among COVID-19 patients with a CRP level of >100 mg/L." (PMID 34300252, 2021). "It is important to note that levels of interleukins, TNFα, and CRP were tested almost exclusively in hospitalized COVID-19 patients." (PMID 34228746, 2021). "Elevated concentrations of cytokines including IL-6, as well as increased CRP and D-dimer concentrations, are common in severe COVID-19 patients, and the uncontrolled inflammatory response has been deemed responsible for the most severe forms of COVID-19." (PMID 34822379, 2021). "In this review, we emphasize the current state of knowledge regarding known CRP for COVID-19 and other viral infections, and potential predictive significance of CRP for organ dysfunction in patients with severe complications and poor outcomes." (PMID 34447386, 2021). "In the case of progressive, severe COVID-19 with high CRP plasma concentrations, pulmonary tissue is irreversibly disposed by the action of CRP." (PMID 34408751, 2021). "As expected the CRP level increased significantly with disease severity of COVID-19 (p value < 0.001)." (PMID 34625911, 2021). "In support of model simulations, PCR cycle time is seen on the decline in the exemplar patient with asymptomatic COVID-19, and the return of C-reactive protein to baseline)." (PMID 34777366, 2021). "Age, multiple comorbidities, a high Charlson comorbidity score, leukocytosis, neutrophilia, higher levels of highly sensitive CRP, ferritin, D-dimer, and AST are associated with poor outcomes among COVID-19 patients." (PMID 34055842, 2021). "In this case, CRP was 28 mg/dL, which was higher than the mean CRP in severe COVID-19 cases, and imaging findings revealed infiltrative shadow and pleural effusion." (PMID 34409491, 2021). "Within the COVID-19 group, older age (mean age 65) (p=0.014), elevated CRP (p=0.012), low O2 saturation (p=0.001), and beta blocker use (p=0.01) were also associated with increased mortality." (PMID 34414048, 2021).
COVID-19 (continued). "These hematological parameter results indicated that for patients with asymptomatic COVID-19, the numbers of different blood cell types were higher, and the CRP level was more stable." (PMID 34722325, 2021). "Some of these parameters have been individually reported to be of predictive significance in COVID-19: CRP levels, blood urea levels signifying kidney involvement, TLC, and old age." (PMID 35047415, 2021). "The laboratory indicators of hypercoagulability in COVID-19 correlate with the overproduction of the inflammatory markers (interleukin-6 and -8, fibrinogen, CRP) and cells (neutrophilia and monocytosis)." (PMID 34381066, 2021). "Significantly elevated levels of ferritin, C-reactive protein and D-dimer were found in all three disease categories of COVID-19 patients." (PMID 34579646, 2021). "Another study reported slight increased CRP levels in 16% of COVID-19 patients 2 months after symptom onset." (PMID 34912863, 2021). "Hospitalized children with COVID-19 are likely to have elevated CRP and LDH and leukocyte indices are less reliable." (PMID 34567235, 2021). "Severe forms of COVID-19 are characterized by an ineffective adaptive immune response that leads to a persistence in C-reactive protein (CRP) and interleukin (IL) -6 elevation." (PMID 33804603, 2021). "Our data confirmed that IL-6, CRP and ferritin levels are higher in severe COVID-19 cases and in patients with fatal outcome and showed negative correlations between these parameters and 25(OH)D." (PMID 34578898, 2021). "In conclusion, CRP serum levels can predict the severity and progression of illness in patients with COVID-19." (PMID 33968148, 2021). "CRP is a standard laboratory parameter of inflammation and commonly elevated in patients with influenza and COVID-19." (PMID 33919094, 2021). "Another study also reported that the initial CRP level on admission was an independent predictor of severe or critical illness in COVID-19 patients." (PMID 34300252, 2021). "Parameters related to inflammation (such as CRP) or coagulation (such as D-dimer) have been correlated to a poor prognosis and have been described as possible predictive biomarkers of COVID-19." (PMID 34207873, 2021). "The bacterial group had higher leukocyte and neutrophil counts than the COVID-19 participants but overlapping CRP and lymphocyte counts, and the COVID-19 group was characterised by high mortality." (PMID 34423323, 2021). "This novel finding encourages the understanding of CRP as a possible prognostic marker in COVID-19 even in older adults." (PMID 34506514, 2021). "Peak CRP and trough lymphocytes have previously been shown to be significant risk factors for AKI in COVID-19, and had a strong temporal relationship with the onset of AKI in our cohort." (PMID 34301204, 2021). "The elevated CRP level of COVID-19 patients is strongly correlated with disease severity and prognosis." (PMID 34955842, 2021). "In a cohort of hospitalised patients with COVID-19, we show that CRP concentrations were significantly higher in patients with positive microbiological cultures as well as in patients who died." (PMID 34496795, 2021). "Overall, it can be observed that the COVID-19 treatment duration is higher for obese patients with high CRP levels and low Albumin levels." (PMID 34207560, 2021). "(2020) studied serum cytokines in COVID-19 patients and found that the CRP level was significantly higher in COVID-19 patients than in healthy individuals." (PMID 34722325, 2021). "Tocilizumab is a treatment option for severe and critically ill COVID-19 patients and it appears to reduce mortality events, especially when CRP level >100 mg/L, P/F ratio 200–300 mmHg, and P/F ratio <200 mmHg." (PMID 33763201, 2021). "High SOFA score, low leukocyte, low lymphocyte, low prealbumin, high AST, high CRP, high LDH and old age, were all significantly associated with death in severe COVID-19 patients by logistic regression analysis (all P < 0.05)." (PMID 33926377, 2021).
COVID-19 (continued). "The most frequent COVID-19 clinical findings during pregnancy were fever (28–100%), mild respiratory symptoms (20–79%), raised C-reactive protein (28–96%), lymphopenia (34–80%), and pneumonia signs in diagnostic imaging (7–99%)." (PMID 34185807, 2021). "In conclusion, MHD patients with COVID-19 who experienced unfavorable outcome had more elevated CRP, IL6 and fibrinogen as well as procalcitonin levels at various points compared to survivors." (PMID 33967613, 2021). "The median post-COVID-19 CRP level was 4.0 mg/L (IQR: 2.0–12.8), and post-COVID-19 fecal calprotectin was 197 mcg/g (IQR: 57.5–653.5) comparable with the pre-COVID-19 infection." (PMID 34858891, 2021). "We also found that high BMI, elderly age, high CRP and 4C-scores correlated with the severity and mortality of COVID-19 patients." (PMID 34822419, 2021). "Second, previous studies have reported that CRP levels in patients with severe COVID-19 increased significantly in the early stages before lung lesions were found on computed tomography." (PMID 34900028, 2021). "For now, CRP apheresis can be considered a safe and potentially effective treatment in patients with a moderate to severe COVID-19 course, specifically when started right after the initial increase of plasma CRP levels or early after the start of ventilation." (PMID 34408751, 2021). "In the first week after symptoms onset, COVID-19 patients showed remarkably decreased levels of lymphocyte count and calcium and slightly increased levels of CRP, LDH, fibrinogen, and D-dimer." (PMID 34021206, 2021). "Blood levels of troponin T, which correlates with higher mortality, showed a positive linear correlation with CRP, indicating a possible role for inflammatory response in COVID-19–related cardiac damage." (PMID 34061779, 2021). "From clinical observations, it was noted elevated concentration of D-D dimer, fibrinogen, and CRP in COVID-19 patients with acute ischemic stroke, suggesting systemic hyperinflammatory and hypercoagulable state." (PMID 34447386, 2021). "Logistic regression analysis showed that highly sensitive CRP was the most significant independent predictor of death among COVID-19 patients who were admitted to an ICU." (PMID 34055842, 2021). "In RECOVERY, over 4000 hospitalized patients with COVID-19 with hypoxia and a C-reactive protein (CRP) ≥75 mg/L were randomized to receive tocilizumab or standard of care." (PMID 34578287, 2021). "CRP levels are elevated in COVID-19 patients, and survivors have been shown to have mean CRP values of approximately 40 mg/L, while non-survivors had mean values of 125 mg/L, indicating a strong correlation with disease severity and unfavorable prognosis." (PMID 34262116, 2021). "Other scientists have shown that laboratory parameters like increased values of C-reactive protein, interleukin-6, lactate dehydrogenase, and D-Dimer are predictors of mortality in COVID-19." (PMID 34182946, 2021). "Studies of critically ill COVID-19 patients identified a state of hyperinflammation characterized by elevated levels of biomarkers including C-reactive protein (CRP), procalcitonin (PCT), and D-dimer." (PMID 34684107, 2021). "The same authors also reported significant increases in ferritin and CRP levels in patients with suspected severe COVID-19, consistent with the current findings." (PMID 33539383, 2021). "Our results revealed persistent higher levels of inflammatory markers such as ESR, CRP, D-dimer, and ferritin in COVID-19 survivors denoting residual systemic inflammatory response." (PMID 34777873, 2021). "We have similarly noted higher levels of NETs release in sera of COVID-19 patients and further highlighted a strong correlation between NETs and inflammatory and coagulation markers, mainly CRP, PCT, WBC count, neutrophil count, and D-dimer." (PMID 34960645, 2021).
COVID-19 (continued). "This is consistent with the role of CRP in COVID-19 evolution: recent investigations demonstrated that CRP is correlated with lung lesion appearance and with the severity of the disease." (PMID 35140702, 2021). "A COVID-19 ARDS Prediction Score model was constructed as CAPS = (1 × age over 60) + (1 × CRP over 5) + (1 × pulmonary infiltration on a chest X − ray over 22%)." (PMID 33897912, 2021). "We found that high-risk factors related to the progression of COVID-19 included procalcitonin (PCT), C-reactive protein (CRP), neutrophils percentage (NEUT%), lymphocytes percentage (LYMPH%), lactate dehydrogenase (LDH) (Wilcoxon rank-sum test, P < 0.001)." (PMID 34485335, 2021). "The severity of COVID-19 can be assessed by detecting inflammatory biomarkers, including high levels of IL-6 and plasma CRP, and the release of these factors is closely related to ARDS." (PMID 34955842, 2021). "It is to be noted that high concentrations of inflammatory biomarkers such as CRP (>200 mg/L) and ferritin (>2,500 ng/mL) at admission have been found to be strong predictors of COVID-19 severity." (PMID 34079487, 2021). "On the other hand, it has been reported that CRP level increases in serum from COVID-19 patients and positively correlates with disease severity." (PMID 35059135, 2021). "Compared to younger patients under 60 years old with COVID-19, levels of CRP, PCT, and IL-10 were all significantly increased in elderly patients." (PMID 33735325, 2021). "When the Australian COVID-19 guideline classification was used instead, only C-reactive protein admission (aHR 1.01 95%CI 1.00–1.01, P = 0.029) remained an independent predictor." (PMID 33606842, 2021). "Compared to suspected COVID-19 patients, the confirmed COVID-19 subjects had a significantly lower oxygen saturation, elevated C-reactive protein, elevated lactate dehydrogenase, and lower lymphocyte count." (PMID 33671699, 2021). "There are laboratory markers available to measure the extent of injury from COVID-19, such as CK-MB, CRP, IL-6 and ferritin." (PMID 33078963, 2021). "The probability for severe disease (i.e., the COVID-19 score) can be calculated using age, albumin, creatinine, high-sensitivity C-reactive protein (CRP), and lactate dehydrogenase (LDH)." (PMID 34123422, 2021). "In line with previous studies, our results showed that higher initial WBC and CRP are associated with more severe cases of COVID-19 patients, as WBC > 1000 cell/mm3 and CRP > 90 mg/L were associated with higher chest CT scores." (PMID 34794467, 2021). "In conclusion, lymphopenia, elevated level of d-dimer, hs-CTnI and hs-CRP were independent predictors of mortality in young adults with severe COVID-19." (PMID 33407543, 2021). "Both IL-1 and IL-6 are critical in regulating CRP levels, which has been found to be prognostic with regard poor outcome in patients with COVID-19." (PMID 34169381, 2021). "Studies have reliably reported increased CRP values in all COVID-19 patients; actually, there seems to be a correlation between CRP level and severity and prognosis, whereby survivors have lower median values (40 mg/L) than non-survivors (125 mg/L)." (PMID 34356272, 2021). "The coagulation function-related indicator D-dimer had a significant positive correlation with CRP and IL-6 in COVID-19 patients." (PMID 34222271, 2021). "CRP had prognostic value in the total population presenting with COVID-19-related symptoms (general signs of illness), while a SARS-CoV-2 positive test per se did not influence the outcome." (PMID 35011944, 2021). "And in agreement with previous studies, we observed an increase in the levels of plasma IL-6, C-reactive protein (CRP) and ferritin in COVID-19 patients in comparison with HC." (PMID 33777054, 2021).
COVID-19 (continued). "Based on the results of our study, a minimum set of analyses composed of hemocytometry plus CRP should be performed in obstetric patients with COVID-19 at admission and during hospitalization, to assess disease severity and follow the evolution of the disease." (PMID 34172816, 2021). "An increasing number of studies of COVID-19 survivors show elevated inflammatory markers, including interleukins and CRP, indicating persistent inflammation in the body months after infection." (PMID 34685427, 2021). "More than half of the patients had COVID-19-related inflammation, reflected by elevated c-reactive protein (CRP)(250/334 [74.9%]) and elevated procalcitonin (140/355 [39.5%])." (PMID 34551393, 2021). "Haematological cancer, a longer-established cancer diagnosis, dyspnoea at diagnosis and raised CRP were indicative of early COVID-19-related death in cancer patients (<7 days from diagnosis)." (PMID 34400804, 2021). "Lymphopenia, increased neutrophil count, and gradually increasing IL-6, C-reactive protein (CRP), troponin, and ferritin levels were all present in patients with more severe forms of COVID-19." (PMID 33841446, 2021). "Our findings suggest that in case of COVID-19, CRP can serve as such a marker that allows alignment of disease trajectories independent of hospital specific policies." (PMID 34307391, 2021). "Our study therefore provides novel information by confirming that the elevation of CRP above 35 g/L predicts fatal outcomes in COVID-19 also in older adults despite the inflammaging that usually characterizes this population." (PMID 34506514, 2021). "Elevated levels of infection-related biomarkers (ESR, IL2R, IL6, IP10, PCT, SF, CRP, TNFα) were detected in many patients with severe COVID-19." (PMID 33542448, 2021). "Several laboratory parameters were described as potential indicators of the severe course of COVID-19 in children, comprising CRP, PCT, LDH, and D-dimers." (PMID 34960635, 2021). "The elevation of CRP to several hundred is higher than what is typically described in adults with COVID-19 (10–30 mg/L in the average adult case, with an average of 50–100 mg/L described in critically ill patients)." (PMID 34903290, 2021). "The percentages of patients with high CRP were 71.93% (41/57) in the moderate COVID-19 group and only 20.00% (3/15) in the asymptomatic COVID-19 group." (PMID 34722325, 2021). "Notwithstanding these limitations, this study provides continued data on the use of CRP as a marker for rapid decline and death for COVID-19." (PMID 33970955, 2021). "The link between CRP and COVID-19 has been emphasized by a study at a tertiary care hospital in Wuhan, where most of the patients in the severe category exhibited increased parameters in comparison with the nonsevere group (57.9–33.2 mg/L)." (PMID 33628256, 2021). "According to our study, older age along with neutrophil count, CRP, fibrinogen, and aPTT levels are independent predictors of mortality in COVID-19 patients with new neurological manifestations at presentation." (PMID 34220483, 2021). "Higher age and high levels of CRP and D-dimers were significant predictors of worse patient outcome for the 199 COVID-19 positive patients." (PMID 33634237, 2021). "Exosomal C-reactive protein (CRP) was detected in the plasma of COVID-19 patients and was positively related to disease severity, suggesting a crucial role for exosomes in CRP transport among host cells." (PMID 34638812, 2021). "There is evidence that LDH and CRP independently predicted ventilation requirements among COVID-19 patients." (PMID 35141240, 2021). "A main factor contributing to COVID-19 severity is believed to be development of the cytokine storm, the uncontrolled release of various inflammatory markers (such as CRP, IL-6, ferritin, tumor necrosis factor α or neutrophil-to-lymphocyte ratio (NLR))." (PMID 34578898, 2021).